SIM1 (SIM bHLH transcription factor 1)
Description:
Transcriptional factor that may have pleiotropic effects during embryogenesis and in the adult.
Synonyms: bHLHe14
Tractability: No criterion of Open Targets' tractability assessment is met for any kind of drug.
Gene: Protein-coding gene on chromosome 6 (100,385,009 to 100,464,935, reverse strand). Ensembl gene ENSG00000112246.
Subcellular location: Nucleus
Subcellular location (Human Protein Atlas): Nuclear speckles
Gene Ontology:
Molecular function: protein binding; DNA binding; DNA-binding transcription factor activity; DNA-binding transcription factor activity, RNA polymerase II-specific; protein heterodimerization activity; RNA polymerase II transcription regulatory region sequence-specific DNA binding; protein dimerization activity
Biological process: nervous system development; regulation of transcription by RNA polymerase II; regulation of DNA-templated transcription; system development; ureteric bud development
Cellular component: chromatin; nucleus
Genetic constraint (gnomAD): Loss-of-function variants: 18 observed, 80.49 expected, observed/expected ratio (o/e) 0.22, 90% interval 0.15 to 0.33. The upper end of that interval is the gene's LOEUF score, 0.33, which puts it in group 1 of 6, group 1 being the genes least tolerant of losing a copy. Missense variants: 939 observed, 1,031.6 expected, observed/expected ratio (o/e) 0.91, 90% interval 0.86 to 0.96. Synonymous variants: 417 observed, 410.58 expected, observed/expected ratio (o/e) 1.02, 90% interval 0.94 to 1.1.
Homologues: Orthologues: macaque SIM1 (99% identical), chimpanzee SIM1 (99% identical), dog SIM1 (99% identical), rabbit SIM1 (98% identical), mouse Sim1 (97% identical), rat Sim1 (96% identical), guinea pig SIM1 (96% identical), pig SIM1 (96% identical), tropical clawed frog sim1 (85% identical), zebrafish sim1a (73% identical), Drosophila melanogaster trh (23% identical), Caenorhabditis elegans hif-1 (15% identical). Paralogues in human: SIM2 (49% identical), NPAS3 (28% identical), HIF1A (23% identical), NPAS1 (23% identical), EPAS1 (21% identical), HIF3A (19% identical), NPAS4 (15% identical).
Diseases named in the same sentence as SIM1 in open-access papers:
SIM1 is named in the same sentence as 35 diseases in open-access papers, as found by Europe PMC text mining. Sharing a sentence is not in itself a finding about the gene and the disease. The quoted sentences say what the papers report.
Obesity (111 papers, 2006 to 2026). Accumulation of substantial excess body fat. "In fact, several studies have identified obesity-associated missense variants in the SIM1 bHLH (Thr46Arg, Glu62Lys), and PAS (Ser71Arg, Ile128Thr, Gln152Glu, Arg171His, Leu238Arg) domains, all of which are involved in forming the heterodimer with ARNT2." (PMID 41516406, 2026). "This is of particular interest as the majority of SIM1 variants that were found to be associated with obesity resulted in modest partial loss of function (30%–80% of WT)." (PMID 41495897, 2026). "Our study identified frameshift deletions, p.(Ser18Ter) and p.(His143Ter), that likely cause haploinsufficiency, consistent with previous reports linking SIM1 loss-of-function mutations to severe obesity and hyperphagia." (PMID 41516406, 2026). "Mice homozygous for Sim1 deficiency die prenatally, whereas heterozygosity and haploinsufficiency lead to the development of early-onset obesity, hyperphagia, hyperinsulinemia, and increased linear growth." (PMID 41516406, 2026). "In this study, we describe eleven patients with early-onset obesity who underwent genetic testing and were found to carry both nonsynonymous and synonymous variants in the SIM1 gene." (PMID 41516406, 2026). "These interpretations align with known pathogenic mechanisms of SIM1 variants implicated in hypothalamic dysfunction and monogenic obesity." (PMID 41516406, 2026). "Loss of SIM1 activity is also associated with early onset obesity and Prader-Willi like features in humans." (PMID 41495897, 2026). "Genetic testing identified a heterozygous SIM1 variant, c.988C>T (p.Ser663Leu), which is likely contributory to his severe, early-onset obesity and metabolic complications." (PMID 41516406, 2026). "This study broadens the range of SIM1 variants linked to monogenic obesity, underscoring their role in hypothalamic development and energy regulation." (PMID 41516406, 2026). "Sim1 is critical for hypothalamic satiety signaling and loss-of-function leads to hyperphagic obesity in mice." (PMID 41495897, 2026). "To date, approximately 30 patients have been reported to have SIM1 variants associated with severe obesity." (PMID 41516406, 2026). "In this study, we identified five rare variants in the SIM1 gene among eleven pediatric patients with severe early-onset obesity." (PMID 41516406, 2026). "Previous studies have demonstrated that SIM1 missense variants can impair transcriptional activity, contributing to the development of obesity." (PMID 41516406, 2026). "Haploinsufficiency and loss-of-function mutations in SIM1 in humans have also been shown to lead to severe early-onset obesity, hyperphagia, and developmental delay." (PMID 41516406, 2026). "This study expands the mutational spectrum of SIM1-linked monogenic obesity, reporting novel likely pathogenic frameshift variants, a missense variant, and a recurrent synonymous variant with a potential splice-site effect." (PMID 41516406, 2026). "Our in vitro evidence supports the PAS-A loop regions directly contacting DNA through a sequence/shape directed mechanism, which is supported by in vivo loss of function in the Sim1.R171H mice leading to hyperphagic obesity." (PMID 41495897, 2026). "Instead, other missense variants cause a variable loss-of-function of the SIM1 and co-segregate with being overweight/obesity." (PMID 40428410, 2025). "Chromosomal deletions involving the 6q14–q21 region, which encompasses several genes including SIM1, have been associated with early-onset obesity and developmental delay." (PMID 40428410, 2025). "Monoallelic, loss-of-function mutations in SIM1 were found to be associated with severe, early-onset obesity, possibly associated with a Prader Willi-like syndrome." (PMID 39237720, 2025). "Evaluation for monogenic causes of obesity demonstrated a variant of uncertain significance in the single-minded 1 (SIM1) gene." (PMID 41323567, 2025).
Obesity (continued). "The patient was found to have a paternally inherited single nucleotide variant of uncertain significance in the SIM1 gene (c.1720A > G) discovered on a genetic obesity panel." (PMID 41323567, 2025). "The pathogenetic mutation of the SIM1 gene evidently plays the main role in our patient’s obesity condition." (PMID 40428410, 2025). "Patients with a monoallelic, pathogenic SIM1 mutations often exhibit neurodevelopmental disorders alongside obesity, mirroring the diverse symptoms observed with chromosome 6q deletions." (PMID 39237720, 2025). "Those genes were associated with severe obesity and Prader-Willi-like syndrome (SIM1), susceptibility to T2D (C2CD4B), and susceptibility to obesity with abdominal fat deposition (MAGEL2)." (PMID 40981068, 2025). "The NGS analysis revealed four variants related to obesity: SIM1, SEMA3C, PLXNA4, and CREBBP gene mutations." (PMID 40428410, 2025). "Deficiency of the SIM1 protein is mostly associated with hyperphagia, weight gain, and obesity, seen both in animal studies and in humans." (PMID 41285899, 2025). "In conclusion, to the best of our knowledge, this case presents for the first time the association of SIM1 gene mutation with other obesity-related variants in a patient with early obesity, hyperphagia, behavioral disorders, and partial diabetes insipidus." (PMID 40428410, 2025). "In a Turkish study involving 105 children with early-onset obesity and analysis of 41 genes, approximately 10.5% of the variants were found in the SIM1, POMC, PCSK1, MC4R, and LEPR genes." (PMID 40149731, 2025). "Disruptions in the leptin–melanocortin–oxytocin pathway or alterations in energy balance regulation can be consequences of SIM1 mutations contributing to the development of obesity." (PMID 40429924, 2025). "This case report describes the clinical history of a child with early onset of severe worsening obesity related to a pathogenic mutation of the SIM1 gene." (PMID 40428410, 2025). "A study linked the SIM1 gene to obesity, announcing that genetic factors influence body weight regulation, which is parallel to animal studies also mentioning dietary variables (see chapter on nutrition)." (PMID 38915776, 2024). "Mutations in the SIM1 gene have been reported in some patients with severe monogenic obesity, but in polygenic obesity, SIM1 polymorphisms are rare." (PMID 39876968, 2024). "These symptoms are likely driven, at least in part, by cranial nerves, including those affected by the patient variants in hs576, an enhancer of the obesity-associated SIM1 gene." (PMID 39019033, 2024). "Patients carrying loss-of-function mutations in SIM1 have also been reported to display obesity and a Prader-Willi syndrome-like phenotype." (PMID 36214963, 2023). "In a Turkish study of 105 children with early-onset obesity that screened 41 monogenic obesity genes, around 10.5% of the cases were found to carry genetic variants in the SIM1, POMC, PSCK1, MC4R, and LEPR genes." (PMID 37329217, 2023). "Sim1 neurons have pronounced effects on satiety and energy homeostasis as both sim1 heterozygous mice, and inducible Sim1-deficient mice, exhibit hyperphagia leading to obesity." (PMID 37443835, 2023). "The loss of miR-7 from Sim1 neurons induces severe obesity, increased energy intake, decreased energy expenditure, increased linear growth, and hyperinsulinemia due to increased insulin secretion." (PMID 36175420, 2022). "Homozygous SIM1 knockout mice die perinatally and postnatal deletion of SIM1 in mice leads to hyperphagic obesity, complicating the search for an erectile deficiency directly linked to altered SIM1 expression." (PMID 36301850, 2022). "For example, it has been shown that both Sim1 deficiency and Sim1 neuron ablation elicit greater obesity in females compared to males." (PMID 36175420, 2022).
Obesity (continued). "The neurons in the PVN express the single-minded 1 transcription factor (SIM1), a factor essential for the neurogenesis of the structures, and genetic variants in the SIM1 have been associated with severe early-onset obesity." (PMID 35447963, 2022). "By using this system to activate Sim1 expression from the healthy intact allele, the obesity phenotype was rescued upon targeting of both, Sim1 promoter or enhancer." (PMID 35097003, 2021). "Heterozygous deletions or mutations in SIM1 have been associated with early-onset obesity with hyperphagia, food impulsivity, and a decrease in the total number of neurons in the PVN." (PMID 33261141, 2020). "The transcription factor SIM1 causes severe obesity due to hyperphagia and reduces the paraventricular nucleus (PVN) of the hypothalamus." (PMID 32982666, 2020). "Deletions and translocations affecting SIM1 cause severe obesity in association with intense orexigenic impulsivity and other features resembling Prader–Willi syndrome." (PMID 30926952, 2020). "Loss-of-function point mutations in SIM1 with variable expressivity and incomplete penetrance also produce a “Prader–Willi-like” phenotype, but also non-syndromic obesity." (PMID 30926952, 2020). "The homozygous patient had severe obesity due to hyperphagia from eighteen months of age and his obese parents were also heterozygous for the same SIM1 variant." (PMID 30991789, 2019). "Although most of the heterozygous SIM1 variants that cause obesity have been described as causing growth retardation and a Prader-Willi-like syndrome in addition to the accompanying obesity, developmental and intellectual capacity was normal in our patient." (PMID 30991789, 2019). "The hyperphagic obesity phenotype of Arnt2R74C/R74C mice is similar to that observed in SIM1-deficient (Sim1+/−) mice." (PMID 30563851, 2018). "Nevertheless, the contribution of SIM1 variants to early-onset obesity have so far only been studied in a few populations." (PMID 28472148, 2017). "One novel SIM1 variant (p.D134N) in one proband out of 126 (0.79%) obese children with early-onset severe obesity was identified." (PMID 28472148, 2017). "Similar to MC4R mutation carriers, SIM1 mutation carriers also have early-onset obesity caused by increased appetite and food seeking behavior persisting into adulthood." (PMID 28472148, 2017). "The inclusion criteria in our study were selected according to the main phenotype features of previously published SIM1 mutation carriers (i.e. severe, early-onset obesity)." (PMID 28472148, 2017). "Although SIM1 gene mutations are a rare cause of obesity, their clinical importance is based on the high risk of morbid obesity (frequently with BMI >50kg/m2)." (PMID 28472148, 2017). "Loss-of-function variants linked to early-onset obesity were previously identified in various regions of the SIM1 gene, particularly in the N-terminal transactivation domain and the PAS1 and PAS2 domains." (PMID 28472148, 2017). "Human patients suffering hyperphagia and obesity, such as those affected by SIM1 gene mutation and by Prader–Willi syndrome, have reduced number and size of OT neurons in the paraventricular nucleus of the hypothalamus." (PMID 26042088, 2015). "Deletions on chromosome 6q16, including SIM1 region, has been similarly associated with obesity and Prader-Willi like phenotype." (PMID 25825681, 2015). "Variants in the SIM1 gene have been associated with obesity in humans and have been shown to reduce transcriptional activity of SIM1 combined with ARNT2." (PMID 25745553, 2015). "In another study, heterozygous mutations in SIM1 were associated with severe obesity accompanied by a neurobehavioral phenotype for a majority of them." (PMID 25825681, 2015). "In humans, disruption of SIM1 gene locus has been found to have caused profound early-onset obesity." (PMID 25806089, 2015).
Obesity (continued). "A de novo balanced translocation between chromosomes 1p22.1 and 6q16.2, which disrupts SIM1, and missense mutations in SIM1 cause severe obesity and a variable phenotype of developmental delay." (PMID 25154910, 2014). "Oxytocin deficits in SIM1 haploinsufficient mice and mutations in the SIM1 gene in humans lead to hyperphagic obesity." (PMID 24065955, 2013). "Mice deficient in the homologous gene, SIM1, also exhibit early onset obesity and increased sensitivity to a high fat diet." (PMID 24260538, 2013). "The transcription factor Single-minded 1 (Sim1) is one of the few genes associated with human monogenic obesity." (PMID 23518828, 2013). "Global ablation of Sim1 neurons, similar to complete deficiency of SIM1, induces obesity that appears to occur due to hyperphagia as a primary defect." (PMID 24260538, 2013). "SIM1 is thought to regulate body weight and is associated with obesity in humans and mice and was, therefore, declared to be one of the candidate genes for meat and carcass quality in cattle." (PMID 24359457, 2013). "Mice with complete (homozygous) or partial (heterozygous) deficiency of SIM1 have hyperphagic obesity with increased sensitivity to a high fat diet." (PMID 24260538, 2013). "Previously we showed that Sim1+/− mice and conditional postnatal Sim1−/− mice exhibit hyperphagia, obesity, increased linear growth and susceptibility to diet-induced obesity, but no decrease in energy expenditure." (PMID 22558467, 2012). "The refined critical region contains only five genes including the obesity-associated SIM1 and the autism-associated GRIK2." (PMID 22102821, 2011). "Partial deficiency of Bdnf, TrkB or Sim1 in mice induces hyperphagia, obesity and developmental features, whereas complete deficiency for Bdnf or Sim1 is lethal and complete deficiency for TrkB dramatically reduces life span." (PMID 22043164, 2011). "Variants in intronic regions of SIM1 were strongly associated with BMI and obesity risk (P = 4 x 10-7) in Pima Indians contrarily to French Europeans for which a major contribution of SIM1 common variants in polygenic obesity susceptibility was excluded." (PMID 22043165, 2011). "A convincing example of ethnic-specific association with obesity has been reported for the SIM1 gene." (PMID 22043165, 2011). "Haplo-insufficiency for BDNF, TrkB and SIM1 has been associated with severe hyperphagic obesity, accompanied by syndromic features in humans." (PMID 22043164, 2011). "Pathogenic variants in the SIM1 gene, a key transcription factor required for the development of the paraventricular nucleus, are a known cause of Prader–Willi-like syndrome, characterized by hyperphagia, severe obesity, and developmental delay." (PMID 41516406, 2026). "Early genetic testing for SIM1 mutations in children with severe obesity and hyperphagia could facilitate personalized interventions, leading to improved long-term metabolic outcomes." (PMID 41516406, 2026). "One of the monogenic obesity genes is the single-minded homolog one gene (SIM1), which encodes a transcription factor located on the long arm of chromosome 6 (6q16.3) and required for neurogenesis, particularly in the development and function of the paraventricular nucleus (PVN)." (PMID 41516406, 2026). "Multiple mouse models have shown that haploinsufficiency in Sim1 results in hyperphagic obesity, however whether partial loss-of-function is sufficient to drive obesity is also yet to be determined." (PMID 41495897, 2026). "Prospectively, given the pathogenetic mechanism underlying obesity-related genes SIM1 and SEMA3-PLXNA, the therapeutic role of setmelanotide can be hypothesized, and is currently being evaluated (ClinicalTrials.gov ID: NCT04963231, NCT05093634)." (PMID 40428410, 2025). "Mutations in the SIM1 gene are a well-documented cause of monogenic obesity." (PMID 40429924, 2025). "SIM1 variants segregate with obesity in extended family studies with variable penetrance." (PMID 40428410, 2025).